APOBEC3B (apolipoprotein B mRNA editing enzyme catalytic subunit 3B)
Diseases named in the same sentence as APOBEC3B in open-access papers (continued):
Sharing a sentence is not in itself a finding about the gene and the disease.
cancer (continued). "This further implicates cancer cell intrinsic mechanism for APOBEC3B and PD-L1 expression correlation." (PMID 29695832, 2018). "It has been well established that APOBEC3B is a molecular driver of mutagenesis in various human cancers." (PMID 29853799, 2018). "Studies have shown that APOBEC3B expression is elevated in a variety of cancer tissues and cell lines, and plays a prominent role in the genesis and evolution of various cancers." (PMID 29853799, 2018). "This hypermutation pattern and high mRNA expression levels of APOBEC3B have been found in several cancer types." (PMID 29642934, 2018). "All studies of APOBEC3B in the last decade show that APOBEC3B will be a promising target for cancer prevention and therapy." (PMID 28572915, 2017). "Here, we discuss current understanding of APOBEC3A and APOBEC3B biology in HPV restriction, evolution, and associated cancer mutagenesis." (PMID 28825669, 2017). "The collective studies suggest that the up-regulation of APOBEC3B in developing tumors promotes cancer progression." (PMID 28572915, 2017). "This notion is inline with observations showing that amount of somatic mutations occurring in APOBEC3-specific sequence context is on average higher in cancer samples with the homozygous APOBEC3B deletion." (PMID 29100317, 2017). "Of the candidate APOBECs capable of such mutagenesis, APOBEC3B was fingered as the most likely culprit—in large part because of its overexpression observed in cancer." (PMID 27716362, 2016). "It will be of great interest to see how generalizable the drug-induced upregulation of APOBEC3B is across cancer cell lines and to assess the impact of a broader group of drugs on APOBEC expression." (PMID 27716362, 2016). "The APOBEC family of enzymes are cytidine deaminases with APOBEC3A and APOBEC3B thought to contribute to DNA damage signatures detected in cancer genomes." (PMID 27650891, 2016). "Leading candidates to account for the overall APOBEC mutation signature in cancer are APOBEC3A (A3A) and APOBEC3B (A3B)." (PMID 27650891, 2016). "The APOBEC3B expression level was significantly higher in the group of cancers with a high NEIL3 expression level than in the group of cancers with a low NEIL3 expression level in 10 of the 13 (76.9%) cancer types." (PMID 27042257, 2016). "We further show that SIVmac239 Vif can prevent APOBEC3B mediated geno/cytotoxicity and degrade endogenous APOBEC3B in several cancer cell lines." (PMID 26544511, 2015). "Our data indicate that the APOBEC3B degradation potential of SIV Vif is an effective tool for neutralizing the cancer genomic DNA deaminase APOBEC3B." (PMID 26544511, 2015). "Relative to ER− cancer cell lines, these results show the down-regulation of both the APOBEC3B and APOBEC3C genes in ER+ cancer cells." (PMID 26682542, 2015). "In other cancers including bladder, cervix, lung and head and neck, APOBEC3B was also upregulated and its preferred target sequence was frequently mutated and clustered." (PMID 25502777, 2014). "In order to reveal the causes of extensive somatic mutations accrued in cancers, a global analysis with the pan-cancer dataset found that APOBEC3B-catalyzed genomic uracil lesions are responsible for a large proportion of mutations in distinct cancer types." (PMID 25071824, 2014). "Additionally, RNA-independent protein–protein interactions have been observed, particularly between APOBEC3B and prefoldin 5 (PFD5), which inhibit the PFD5-mediated-degradation of the oncogene cMyc, suggesting a role for APOBEC3B in cancer pathways." (PMID 40143363, 2025). "In particular, APOBEC3A (A3A) and APOBEC3B (A3B) play important roles in cancer." (PMID 41055562, 2025). "Our findings make the case that APOBEC3B is not merely a passive mutator but a major orchestrator of replication stress-induced genomic instability in BRCA2-mutant cancers." (PMID 41162355, 2025).
cancer (continued). "Using tumor cell lines for a number of cancers that included colorectal, breast, bladder, lung, and esophageal tumor cell lines, it was shown that cyclic hypoxic conditions induce the expression and activity of APOBEC3B." (PMID 41373684, 2025). "APOBEC3A and APOBEC3B expression is detected in many cancer types and their own classified Catalogue of Somatic Mutations in Cancer (COSMIC) mutational signatures [single base substation signatures (SBS) 2 and 13] are present in over 50% of human cancer types." (PMID 38976757, 2024). "Similarly, a previous cell line study also reported a relationship between APOBEC3B overexpression and anti-cancer activity of ATR inhibition." (PMID 38827321, 2024). "APOBEC3A and APOBEC3B are the prominent mutagenic drivers in several cancer types, giving rise to a distinct mutational signature (SBS2 and SBS13) that can be distinguished from dMMR and identified by cancer genome sequencing and analysis." (PMID 38201511, 2023). "In none of these analyses was there evidence of cancer predisposition for carriers of an APOBEC3B truncating mutation." (PMID 37510234, 2023). "Moreover, both APOBEC3A and APOBEC3B display cytidine-deaminase-independent roles in carcinogenesis that add complexity when it comes to comprehending their roles in cancer." (PMID 36980505, 2023). "Synergic action between the FHIT and APOBEC3B in cancer has been observed in several cancers." (PMID 36831487, 2023). "Taken together with the fact that APOBEC3B binds single-stranded DNA and RNA and preferentially deaminates DNA, these results support a mechanism in which APOBEC3B regulates R-loops and contributes to R-loop mutagenesis in cancer." (PMID 37735199, 2023). "Among APOBEC family, APOBEC3B is the most widely investigated member in various cancers." (PMID 35673559, 2022). "Here we conducted pan-cancer analysis of APOBEC3B, explored the relationship between APOBEC3B expression levels and clinical prognosis, immune cell infiltration, TMB or MSI, as well as the mutation sites, interactive genes and involved pathways of the APOBEC3B gene." (PMID 35918642, 2022). "Recent studies have found that APOBEC3B provides a potential link among inflammation, cancer, and immune processes, which may be a novel finding for the non-enzyme-dependent function of APOBEC3B." (PMID 36203448, 2022). "Therefore, a larger sample size is needed to test the role of APOBEC3B in the survival and prognosis of different types of cancers." (PMID 35918642, 2022). "The physiologically relevant gene substrates for APOBEC3B that change molecular mechanisms, give rise to cancer phenotypes and may be important targets for pharmaceutical development are still being explored." (PMID 35872531, 2022). "Recent research has illustrated that APOBEC3B, which has a unique role in the cancer cell cycle, might be a potential therapeutic target in the treatment of cancer." (PMID 36249021, 2022). "APOBEC3A and APOBEC3B often function as oncogenes in these cancers." (PMID 35902635, 2022). "Moreover, in the APOBEC family, APOBEC1, AID, and APOBEC3B are also closely related to cancer, but their related molecular mechanisms still need to be further explored." (PMID 36203448, 2022). "In this study, we principally explored the potential role that APOBEC3B (NM_004900.4 for the mRNA or NP_004891.4 for the protein) might play during cancer initiation and progression." (PMID 35918642, 2022). "When it comes to APOBEC3B, it is the most widely investigated member of APOBEC family and causes a variety of mutagenic outcomes 55, but its biological impact on cancers still remains unclear, even contrary." (PMID 35673559, 2022). "Here, we conducted a pan-cancer analysis of APOBEC3B using the TCGA project." (PMID 35918642, 2022). "In addition, we used the ‘Pathological Stage Plot’ module of GEPIA2 to analyze the relationship between the expression of APOBEC3B and the pathological stages of cancers." (PMID 35918642, 2022).
cancer (continued). "The role of APOBEC3B in inflammation, cancer, and immunity suggests that– APOBEC3B may be used as an immunomodulatory factor to promote tumor progression by altering the immune microenvironment." (PMID 36203448, 2022). "On the contrary, chemotherapy could induce replication stress and higher APOBEC3B expression, which may ultimately lead to the development of an increase in clones during chemotherapy for cancers resistant to cytotoxic drugs." (PMID 33925044, 2021). "Although several APOBEC3s have been implicated in cancer mutagenesis including APOBEC3A (A3A) and APOBEC3H (A3H), a particularly strong case can be made for APOBEC3B (A3B)." (PMID 32985974, 2020). "In the present study, we found that APOBEC3B expression gradually increased from 24 to 72 h after IR in all three cancer cell lines tested, and we speculate that the upregulated expression was probably the result of a DNA damage response." (PMID 32880638, 2020). "Finally, depletion of UNG was recently shown to induce synthetic lethality in APOBEC3B overexpressing cancers." (PMID 32264925, 2020). "Therefore, we performed a functional knockdown screen of 92 cancer associated transcription factors and identified GATA3, SPDEF, IRF9, and YY1 as candidate transcriptional activators/repressors for APOBEC3B gene expression." (PMID 32934779, 2020). "APOBEC mutational activity in cancer can be sustained by two main isoforms: APOBEC3A and APOBEC3B." (PMID 32317634, 2020). "Strikingly, a germline deletion linking APOBEC3A and APOBEC3B loci, which enhances APOBEC3A expression and APOBEC-derived mutagenesis in cancer, has been associated with higher neoepitope loads and immunologic infiltrate and negatively correlated with LNM in BC." (PMID 33352945, 2020). "Therefore, APOBEC3B expression levels in cancer cells would be expected to influence the effects of radiation therapy and patient prognosis." (PMID 32880638, 2020). "Increased expression of APOBEC3B in response to IR could contribute to acquisition of radiation resistance and new properties in cancer cells." (PMID 32880638, 2020). "Since APOBEC3B is a driver of cancer genomic diversity, we hypothesize that its over-expression may have two therapeutically opposing consequences." (PMID 32034147, 2020). "That the APOBEC3A, APOBEC3B, and APOBEC3G footprints are more abundant in comparison with the APOBEC1 and AID motifs suggests an important role for these three deaminases in generating somatic C:G>A:T mutations in human cancers." (PMID 30759888, 2019). "However, misregulated APOBEC3B can also be detrimental by inflicting APOBEC signature C-to-T and C-to-G mutations in genomic DNA of multiple cancer types." (PMID 30723127, 2019). "The transversions associated with APOBEC1, APOBEC3A, and APOBEC3B were found to be more abundant in comparison with APOBEC3G and AID, suggesting a role of these three deaminases in generating C:G>G:C somatic mutations in human cancer." (PMID 30759888, 2019). "It was assumed to suppress cancer progression through inhibiting APOBEC3B expression." (PMID 29695832, 2018). "Since APOBEC3B is upregulated in numerous cancer types we wondered if these findings could be explained by the micro-environment of the distant site." (PMID 28141868, 2017). "Whether APOBEC3B mutagenic activity is a potential cancer driver or a downriver effector remains an open question, and the mechanism of APOBEC3B upregulation in cancer cells needs further evidence." (PMID 28572915, 2017). "Above all, APOBEC3B may represent an important marker for various human cancers and a strong candidate for targeted intervention, especially given its essential nature to tumor progression and heterogeneity." (PMID 28572915, 2017). "APOBEC3B, a DNA cytosine deaminase, is overexpressed in a wide spectrum of human cancers." (PMID 28572915, 2017). "Increasing evidence have shown that APOBEC3B may be a predominant mutagenic agent having effects on the genesis and evolution of various cancers." (PMID 28572915, 2017).
cancer (continued). "Moreover, a significant positive correlation was found between the NEIL3 and APOBEC3B expression levels in 10 (76.9%) cancer types." (PMID 27042257, 2016). "Finally, NEIL3 expression was shown to be correlated with the expression of APOBEC3B, a potent inducer of mutations, possibly explaining why an increased NEIL3 expression level was associated with the somatic mutation load in cancer." (PMID 27042257, 2016). "Further research into the potential role of APOBEC3B genotype as a predictive biomarker for cancer prevention or anticancer immunotherapy may be warranted, particularly for Asian women." (PMID 27233495, 2016). "For several cancer types (breast, bladder, cervical, head and neck and lung) an APOBEC mutation pattern was identified and the APOBEC-mediated mutagenesis was found to correlate with APOBEC mRNA levels, particularly with APOBEC3B." (PMID 27527602, 2016). "We conclude that APOBEC3B overexpression and Fhit-loss induced DNA damage are independent events that, when occurring together, result in a significantly increased frequency of APOBEC-induced mutations that drive cancer progression." (PMID 25401976, 2015). "Overall, a compelling case has been made for APOBEC3B mutagenesis in breast and additional cancers." (PMID 25848704, 2015). "More recently, several studies have converged upon the innate immune DNA cytosine deaminase APOBEC3B (A3B) as a significant source of genomic uracil lesions and mutagenesis in multiple human cancers, including those of the breast, head, and neck, cervix, bladder, lung, ovary, and other tissues." (PMID 26180547, 2015). "Such phenomena are consistent with our findings that there is less functional interaction between APOBEC3C and APOBEC3B proteins, suggesting they may perform different roles in cancer cells." (PMID 26682542, 2015). "Direct measurements of APOBEC3B mRNA or protein levels, perhaps in combination with ‘reading’ its mutagenic signature, would allow tumors to be grouped into APOBEC3B risk categories (analogous to assays for microsatellite instability in MMR-defective cancers)." (PMID 25848704, 2015). "A new example is the DNA cytosine deaminase APOBEC3B, which was identified recently as a source of DNA damage and mutagenesis in breast, head/neck, cervix, bladder, lung, ovary, and to lesser extents additional cancer types." (PMID 25848704, 2015). "A cooperative role in APOBEC3B mutagenesis is furthermore attributed to the tumor suppressor fragile histidine triad protein (FHIT), which is known to cause DNA damage upon loss of protein activity in normal and cancer cells." (PMID 26097867, 2015). "Also, facilitated by massive sequencing of tumor samples, a widespread APOBEC3B fingerprint was found among many types of cancers." (PMID 25341666, 2014). "Although gene expression data on APOBEC3B enzymes provide support for a role in cancer mutagenesis through U:G mismatch intermediates, the enzyme preference for single-stranded DNA may limit its activity genome-wide." (PMID 24705290, 2014). "Our studies strongly suggest a direct role for APOBEC3B in cancer mutagenesis beyond tumor onset." (PMID 25123150, 2014). "This type of clustered mutations and mutation ‘showers’ have recently been shown to be functionally linked with cancer development through the action of APOBEC (apolipoprotein B mRNA-editing enzyme, catalytic polypeptide-like) cytidine deaminases, especially APOBEC3B." (PMID 24244712, 2013). "Also, our PCa patients showed no APOBEC3A and APOBEC3B germline predispositions, as previously reported in other cancers, including rs12628403, rs1014971." (PMID 41282084, 2025). "It is speculated that APOBEC3B could induce genome instability in various cancers." (PMID 36249021, 2022).
cancer (continued). "In addition, given a role for APOBEC3B in cancer mutagenesis, it may also be possible for information from the interaction to be used to develop DNA deaminase inhibitors." (PMID 35476445, 2022). "This further suggested that APOBEC3B might play different roles in different cancer types." (PMID 35918642, 2022). "Thus, APOBEC3B may regulate APOBEC3A mutagenesis across a broader range of cancers, possibly through regulating the expression of APOBEC3A." (PMID 35859169, 2022). "Although identification of specific inhibitors against APOBEC3A and 3B are still ongoing, the development of APOBEC3A-ssDNA and APOBEC3B-ssDNA co-crystal structures may be helpful for developing structure-based molecule inhibitors that could be useful in cancer therapy." (PMID 34578402, 2021). "APOBEC3B expression also had the strongest correlation with mutation counts in RCC as opposed to other cancer categories; however, such correlations for APOBEC3B were somewhat weaker and less significant (ρ ≤ 0.86, padj ≥ 0.16) than those for APOBEC3A (data not shown)." (PMID 29642934, 2018). "However, how APOBEC3B expression is regulated during cancer evolution still remain elusive." (PMID 29695832, 2018). "Therefore APOBEC3B inhibition may decrease the rate of cancer progression and keep the stability of the targeted genome." (PMID 28572915, 2017). "Our demonstration of a correlation between NEIL3 expression and APOBEC3B expression may explain why an increase in NEIL3 expression is associated with the somatic mutation load, since APOBEC3B is involved in mutagenesis in multiple distinct human cancers." (PMID 27042257, 2016). "Interestingly, the significantly positive correlation between the number of C>T/G>A mutations per tumor exome and APOBEC3B mRNA levels is observed in ER+ cancers (ρ = 0.32, P = 7.09 × 10−15), but not in ER− cancers (ρ = 0.04, P = 0.60)." (PMID 26682542, 2015). "Our finding also suggests that, as TpC* mutations primarily occur early in the development of the cancer, therapeutic targeting of APOBEC3B may not be suitable in non-muscle invasive bladder cancer." (PMID 26553077, 2015). "We demonstrate that IL-6 trans-activates the expression of APOBEC3B and trans-inactivates the expression of UNG, thus unbalancing APOBEC3B/UNG and facilitating cancer evolution and development." (PMID 36831487, 2023). "Compared to ANTs, APOBEC3B was significantly downregulated in COAD and THCA, while upregulated in the other 14 cancer types." (PMID 35673559, 2022). "Finally, we show that APOBEC3B-induced heteroclitic neoepitope vaccines are effective against different tumor types, growing in different anatomic locations, indicating that this represents a technically simple, widely applicable method to exploit neoepitopes for cancer immunotherapy." (PMID 32034147, 2020). "Further studies have attributed specific hypermutation signatures across all cancers to the APOBEC family, including APOBEC3B." (PMID 31277598, 2019). "A strong positive and highly significant correlation between APOBEC3B and APOBEC3A expression was also observed in the pan-cancer analysis (ρ = 0.714, padj < 0.001, n = 1036, Ntests = 10)." (PMID 29642934, 2018). "Expression levels of APOBEC3B showed strong and statistically significant positive correlation with APOBEC3A expression in 21 cancer categories (ρ between 0.576 and 1.000; padj < 0.05)." (PMID 29642934, 2018). "We observed a bimodal distribution of APOBEC3B expression and unimodal distributions of APOBEC3A, REV1, UNG, and FHIT in the pan-cancer dataset." (PMID 29642934, 2018).